AR (androgen receptor)
Diseases named in the same sentence as AR in open-access papers (continued):
Sharing a sentence is not in itself a finding about the gene and the disease.
meningioma (7 papers, 2006 to 2024). A generally slow growing tumor attached to the dura mater. "After analysis of data from seven related articles, androgen receptors (AR) expression was found in 45.5% of meningiomas (95% CI: 23–68)." (PMID 36765937, 2023). "AR expression appears variable, most often found in more than 50% of meningiomas, and would be greater in women than men." (PMID 36765937, 2023). "In another study, weak or positive AR expression was observed in 38.8% of the 162 meningioma specimens (grades I, II and III) studied using immunohistochemistry on TMA sections." (PMID 32903787, 2020). "Estrogen receptor (ERs) is expressed at a low level in about 10% of meningiomas patients, while progesterone (PRs) and androgen receptor are expressed in 70% of meningiomas patients." (PMID 32974188, 2020). "In disagreement with our work, immunohistochemical analysis of 39 meningiomas of all grades showed AR was expressed in varying intensities in 67% of cases, with a predominance for females (86%) compared with males (44%) and the finding was significant." (PMID 32903787, 2020). "Amongst the benign tumors, AR expression has been demonstrated in nasopharyngeal angiofibromas, hepatic adenomas, and meningiomas." (PMID 17020615, 2006). "The objective of this study was to synthesize the epidemiological, clinical, and histopathological data of meningiomas of any setting according to the expression of the hormone receptors PR, ER, AR, and SR in a physiopathological and prognostic aim, using a systematic review." (PMID 36765937, 2023). "Immunostaining of AR was observed in proliferative endothelial cells of tumor microvasculature, together with nuclear labeling, leading to the conclusion that AR was related to Ki67 and tumor grade, and probably participates in the growth processes and neoangiogenesis of meningiomas." (PMID 32903787, 2020). "Series of meningiomas and respective percentages of AR expression." (PMID 32903787, 2020). "And the progesterone and androgen receptor-positive rate in meningioma tissues were relatively high, so progesterone and androstenedione in the culture medium might contribute to the growth and proliferation of meningioma cells." (PMID 22754374, 2012). "In addition, progesterone and androgen receptor-positive rates in meningioma tissues are about 60~90% and 65%, respectively." (PMID 22754374, 2012). "Androgen receptor antagonists have not yet been tested, and only everolimus with octreotide therapy has a satisfying effect against meningiomas." (PMID 37686527, 2023). "On the other hand, low AR expression and the absence of a relation with recurrence in most studies suggest that AR does not influence on the pathogenesis and growth of grade I meningiomas." (PMID 32903787, 2020). "There have been no reports of androgen receptor antagonists in meningiomas." (PMID 32974188, 2020).
multiple sclerosis (7 papers, 2017 to 2024). A progressive autoimmune disorder affecting the central nervous system resulting in demyelination. "Here, we show a predominant microglial AR expression in demyelinated lesions from female mice and women with multiple sclerosis, but virtually undetectable AR expression in lesions from male animals and men with multiple sclerosis." (PMID 36949062, 2023). "Our results uncover a new persistent effect of postnatal AR signaling, with implications for neurodevelopmental disorders and sex differences in multiple sclerosis." (PMID 29107990, 2017). "AR are expressed in spinal cord neurons, and neuroprotective effects of T have been documented in different CNS lesion systems and also in men with multiple sclerosis." (PMID 38291527, 2024). "Further, results from this study may provide mechanisms for how AR signaling attenuates inflammation in other inflammatory diseases with a female predominance, including lupus and multiple sclerosis." (PMID 35025767, 2022).
Parkinson disease (7 papers, 2010 to 2025). A progressive degenerative disorder of the central nervous system characterized by loss of dopamine producing neurons in the substantia nigra and the presence of Lewy bodies in the substantia nigra and locus coeruleus. "Because AR45 appears to be the predominant AR in the SNpc, it may have clinical relevance in the progressive motor disorder Parkinson’s disease (PD), resulting from the loss of TH+ neurons in the SNpc." (PMID 28856243, 2017). "It is worth noting that these three HDAC proteins do not alter expression of other transgenes, such as a polyglutamine-containing androgen receptor in a Drosophila model of SBMA or uas-alpha synuclein in a Drosophila model of Parkinson's Disease." (PMID 21170301, 2010). "Both bisphenols affected pathways such as “PARK2/PINK1/UCHL1 in Young Onset Parkinson’s Disease”, “TNF activation of NF-kB Expression Targets”, and “Androgen Receptor/FKBP5 Signaling”." (PMID 41012393, 2025).
Pca (7 papers, 2014 to 2025). "At present, through research on each key target associated with AR, the corresponding drugs for each site of action have been developed and applied in the treatment of patients with PCa at each stage." (PMID 38965120, 2024). "In addition to AR splice variant formation, previous studies have suggested that abnormal hyperactivation of glucocorticoid(GR) signalling contributes to the progression of hormone-dependent Pca to CRPC in patients receiving ADT10,11." (PMID 31727962, 2019). "We found that mRNA expression levels of six genes were upregulated in 22Rv1 cells compared to those in the LNCaP cells, indicating that these genes are upregulated in AR-positive CRPC compared with hormone therapy-sensitive Pca." (PMID 37950047, 2023). "BMS-345541 and PS1145 are novel compounds that are highly selective for IKK-beta, leading to inhibitory activity, thus triggering cell apoptosis in androgen receptor-expressing Pca cell lines." (PMID 36900412, 2023). "AR is expressed in the majority of primary and metastatic prostate cancer (Pca), and its activation and expression are closely related to the occurrence and development of primary and metastatic Pca and the regulation of tumor proliferation, invasion and metastasis." (PMID 38965120, 2024). "Androgen receptor (AR) signaling plays a critical role in driving PCa initiation and progression, thereby establishing AR signaling as a principal therapeutic target." (PMID 41488631, 2025). "During androgen-dependent progression, PCa cells largely rely on the androgen receptor (AR) for both growth and survival." (PMID 36900412, 2023). "Although the research on AR in PCa is relatively mature, studies on AR in RCC are rare." (PMID 38965120, 2024). "In vitro cell lines: RWPE-1 (normal prostate epithelial cells), LNCaP (hormone-sensitive, AR-positive), 22RV1, PC3, VCaP, DU145, RM-1Murine models: Subcutaneous xenografts established using RM-1 cells.Clinical specimens: Paired Pca tissues and adjacent normal tissues from 95 patients." (PMID 41488631, 2025).
Primary amenorrhea (7 papers, 2010 to 2026). "In this study, we identified a novel splice site mutation in the AR gene, c.2450-1G > A, in a 46,XY patient presenting with a female phenotype, including primary amenorrhea and classical features of AIS, confirmed by chromosomal analysis and ultrasonography." (PMID 42021352, 2026). "This insertion mutation was predicted to produce frame shift mutation and resulted in truncated form of the AR protein, implicating it in the phenotype observed with primary amenorrhea." (PMID 25606384, 2014). "Furthermore, a 16-year-old Turkish patient with a 46,XY karyotype, female external genitalia, and primary amenorrhea was reported to have a novel hemizygous frameshift mutation in the AR gene (c.1629_1630insA)." (PMID 40699748, 2025). "Case presentation: We herein present the case of a 14-year-old adolescent with primary amenorrhea and suspected delayed puberty whose diagnostic journey led to the identification of CAIS through the demonstration of a novel AR variant (c.159_207del)." (PMID 39452478, 2024). "It is perplexing that the patient 19’s clinical manifestations align with CAIS (female with juvenile external genitalia, blind end of vagina, testis located in inguinal region, admitted with primary amenorrhea), yet no mutation of AR gene was detected." (PMID 40247401, 2025). "In our 31 adolescents with primary amenorrhea due to 46,XY DSD, 16 showed high testosterone concentrations and, as expected, AR gene mutation was a major cause among those who presented with breast development (B5) contrasting with an absence of pubic hair (P1) (data not presented)." (PMID 20302644, 2010).
serous carcinomas (7 papers, 2010 to 2025). "Subset analysis of serous carcinoma's (n = 90), revealed that the association between AR and ER positivity remained significant, whereas the relationship with PR expression was lost." (PMID 20565760, 2010). "However, subset analysis in serous carcinomas (n = 90) revealed that increased AR expression was associated with a prolonged OCSS (p = 0.034)." (PMID 20565760, 2010). "Our results indicate a high rate and a strong expression of AR in both categories of serous carcinomas." (PMID 40392873, 2025). "More recent studies have also shown AR expression in nearly all OC subtypes, with higher levels seen in serous carcinomas." (PMID 40392873, 2025). "Further investigation has demonstrated that androgen stimulation promotes cancer progression through regulation of the cell cycle in AR-positive serous carcinomas." (PMID 40392873, 2025). "AR, ER, and PR expressions were assessed in 62 cases which were categorized into: low-grade serous carcinoma (LGSCA), high-grade serous carcinoma (HGSCA), clear cell carcinoma (CCCA), ovarian endometrioid carcinoma (OECA), and granulosa cell tumor (GCT)." (PMID 40392873, 2025). "Another example is expression of AR in 92% of the serous carcinomas but the ER and PR counterparts are in 85% and 62%." (PMID 37725629, 2023). "A noticeably higher AR expression was mainly stated in the subgroup of serous carcinomas, reaching 50%." (PMID 33808541, 2021). "In another immunohistochemical study using surgical specimens, the levels of AR expression were significantly higher in serous carcinomas (n = 7) than in normal/inactive ovary tissues (n = 7)." (PMID 30791431, 2019). "In a recent study, it was noted that 70% of serous cancers and 50% of carcinosarcoma also show AR expression and high levels of AR expression was noted in half of serous carcinoma." (PMID 29747687, 2018). "In ovarian high-grade serous carcinomas, immunohistochemical expression of AR correlated with the S-phase fraction and AR expression decreased with platinum-based chemotherapy." (PMID 25823848, 2015). "AR expression in primary tumors correlated with expression in metastases (R= 0.95, p < 0.001) particularly when serous carcinomas (n = 90) were analyzed separately (R = 0.97, p < 0.001)." (PMID 20565760, 2010). "Also, both types of serous carcinomas demonstrate similar patterns of ER and AR co-expression, and any significant differences between the three hormone receptors could be attributed to lower rates of PR expression." (PMID 40392873, 2025). "15/77 (19.48%) of endometrioid cancers and 3/7 (42.28%) cases of serous carcinoma showed AR expression; while none of the cases of clear cell or carcinosarcoma revealed AR expression." (PMID 29747687, 2018). "15/77 (19.48%) of endometrioid cancers and 3/7 (42.28%) cases of serous carcinoma showed androgen receptor expression; while none of the cases of clear cell or carcinosarcoma revealed androgen receptor expression." (PMID 29747687, 2018). "Notably, a significant expression of AR was seen in cases of high-grade serous carcinoma and clear cell carcinoma in the absence of ER and PR expression." (PMID 40392873, 2025).
Abdominal obesity (6 papers, 2016 to 2025). Excessive fat around the stomach and abdomen. "Knockdown of hypothalamic AR is closely associated with reduced insulin sensitivity and central obesity." (PMID 37900128, 2023). "Further, adipose-specific AR gene knockout mice were more vulnerable to high-fat diet-induced central obesity and glucose intolerance." (PMID 37900128, 2023). "It has also been hypothesized that increased androgen receptor density in abdominal fat depots may facilitate regional fat accumulation, further strengthening the link between AGA and abdominal obesity." (PMID 41312577, 2025).
adenoma (6 papers, 2013 to 2025). A neoplasm arising from the epithelium. "Malignant tumors that showed low AR and ER expression in our 2021 study were less prone to antihormonal treatment than epithelioma and adenoma cases." (PMID 36766353, 2023). "Conversely, immunohistochemical analysis revealed that over 50% of corticotrope adenomas and normal corticotrope cells express the androgen receptor." (PMID 32183012, 2020). "Tumors in the adenoma and epithelioma groups, which showed high AR and ER expression in the previous 2021 study, were subject to a significantly greater and faster reduction in diameter over the course of treatment when receiving antihormonal therapy compared to tumors in the carcinoma group." (PMID 36766353, 2023). "Androgen receptor (AR) is expressed in 74 % of gonadotropinomas, and DLK1 is silenced in non-functioning adenomas, while it is highly expressed in functional adenomas." (PMID 23756599, 2013). "The presence of epithelial atypia within a PA (ranging from isolated AR expression to apocrine metaplasia to overtly dysplastic/malignant epithelial cells) does not portend recurrence or metastasis if the atypia is confined within the borders of the adenoma and negative margins are achieved." (PMID 40938457, 2025).
astrocytomas (6 papers, 2004 to 2025). "Among IDH-mutant LGGs, AR expression was more frequent in IDH-mutant astrocytomas compared with IDH-mutant oligodendrogliomas and 1p19q codeleted (p= 0.02)." (PMID 41153666, 2025). "It has been reported that AR expression is higher in patients with GBM as compared with normal brain tissue from the same patients, and that the expression of AR increases as the degree of malignancy of astrocytomas progresses, being grade IV (GBM) the ones that present the highest protein content." (PMID 30778332, 2019).
bone metastasis (6 papers, 2021 to 2024). Transfer of a neoplasm from its primary site to bones. "Because the majority of clinical mPCs progress following ADT and ARSI treatment with the retention of AR signaling, and patients often harbor bone metastases, we further tested B7H3-PBD-ADC activity against a late-stage ARPC bone metastasis model." (PMID 37725435, 2023). "He had documented local and distant failure (bone metastasis) 0.4 years after diagnosis and was started on a salvage nonsteroidal androgen receptor inhibitor but died from further progression shortly thereafter." (PMID 38539538, 2024).
carcinosarcoma (6 papers, 2010 to 2025). A malignant tumor composed of a mixture of carcinomatous and sarcomatous elements. "Likewise, AR expression is seen in 100% of carcinosarcomas while ER and PR are co-expressed in 67% and 50% of the cancers respectively." (PMID 37725629, 2023). "Carcinomatous and sarcomatous components were both positive for AR in carcinosarcomas." (PMID 37725629, 2023). "Moreover, there is evidence that in most carcinosarcomas, the carcinomatous and the sarcomatous components are genetically the same, as shown for 21 of 25 carcinosarcomas (84%) using the human androgen receptor (HUMARA) for detection of X-chromosome inactivation." (PMID 20368795, 2010). "Traditionally, type II ECs are considered to be hormonally independent; there are only limited reports of ER and PR expression, with no previous data on AR and ERβ expression in serous and clear-cell carcinomas and carcinosarcomas." (PMID 26930451, 2016).
endothelial dysfunction (6 papers, 2020 to 2025). In vascular diseases, endothelial dysfunction is a systemic pathological state of the endothelium (the inner lining of blood vessels) and can be broadly defined as an imbalance between vasodilating and vasoconstricting substances produced by (or acting on) the endothelium. "This schematic diagram illustrates how AAS abuse triggers androgen receptor-mediated hypertrophy, endothelial dysfunction, oxidative stress, and inflammation, ultimately leading to myocardial fibrosis, arrhythmias, and increased cardiovascular risk." (PMID 41303522, 2025). "It is also possible that the increase in aldosterone seen during high AR signaling can contribute to endothelial dysfunction." (PMID 37571268, 2023). "These factors suggest that supra-physiological androgen doses can lead to endothelial dysfunction, potentially due to exaggerated AR signaling activity." (PMID 37571268, 2023). "Meanwhile, it has been reported that hyperuricemia induced endothelial dysfunction via regulation of AR, while inhibition of AR or degradation of ROS could restore endothelial function." (PMID 32685502, 2020). "The relationship between AR, FLCN, and endothelial dysfunction requires further study." (PMID 34447638, 2021).
epilepsy (6 papers, 2018 to 2026). A brain disorder characterized by episodes of abnormally increased neuronal discharge resulting in transient episodes of sensory or motor neurological dysfunction, or psychic dysfunction. "It is interesting to note that in patients with epilepsy, their temporal lobectomy tissue also showed some degree of elevation of AR expression when compared to brain tissues from autopsy of normal brain which again suggests the possible involvement of AR in the pathologic process of brain." (PMID 34094902, 2021). "Similarly, lobectomy tissue from epilepsy patients showed very low AR expression detected in very few cells." (PMID 34094902, 2021).
esophageal squamous cell carcinoma (6 papers, 2014 to 2025). Esophageal squamous cell carcinoma (ESCC) is a type of esophageal carcinoma (EC) that can affect any part of the esophagus, but is usually located in the upper or middle third. "Esophageal squamous cell carcinoma (ESCC) progression is driven by androgen receptor (AR) signaling, while small nucleolar RNAs (snoRNAs), classically involved in ribosomal RNA processing, are increasingly recognized for non-classical roles in cancer." (PMID 41178567, 2025). "The growth of esophageal squamous cell carcinoma (ESCC) is facilitated by YY1BM, a 21 aa micropeptide encoded by LINC00278, which blocks the connection between YY1 and androgen receptor (AR), reducing eEF2K production through the AR signalling pathway." (PMID 38622617, 2024). "Emerging evidence suggests that AR is involved in the growth of esophageal squamous cell carcinoma." (PMID 38136265, 2023). "However, how AR exerts its functions in the invasion of esophageal squamous cell carcinoma remains unknown." (PMID 38136265, 2023). "In esophageal squamous cell carcinoma (ESCC), the Y-linked lncRNA LINC00278 encodes a Yin Yang 1 (YY1)-binding micropeptide, designated YY1BM, which inhibits the interaction between YY1 and androgen receptor (AR)." (PMID 39443468, 2024).
head and neck cancer (6 papers, 2013 to 2024). A primary or metastatic malignant neoplasm affecting the head and neck. "30.0% of the all the microRNA studied in head and neck cancer to determine patient's prognosis was enriched in one network to regulate AR gene expression." (PMID 28903437, 2017). "Some subtypes of head and neck cancer show moderate AR positivity, while others have reports of sporadic tamoxifen sensitivity." (PMID 29057879, 2017).